GRB2 (growth factor receptor bound protein 2)
Diseases named in the same sentence as GRB2 in open-access papers (continued):
Sharing a sentence is not in itself a finding about the gene and the disease.
thymoma (1 paper, 2020). A neoplasm arising from the epithelial cells of the thymus. "In the thymoma cell line Thy0517, it was found that the expression of GRB2 and the phosphorylation levels of BRAF, MEK1/2, and ERK1/2 in the MAPK pathway were positively correlated with the change in KITLG." (PMID 32463597, 2020). "To confirm this point, we used established AB thymoma cell line Thy0517 and the results showed that KITLG suppression could downregulate the expression of GRB2, p‐BRAF, p‐MEK1/2, and p‐ERK1/2, whereas KITLG overexpression had a profound activating effect on the MAPK pathway in Thy0517." (PMID 32463597, 2020).
triple-negative breast carcinoma (1 paper, 2021). An invasive breast carcinoma which is negative for expression of estrogen receptor (ER), progesterone receptor (PR), and human epidermal growth factor receptor 2 (HER2). "Therefore, in cells depleted for a given RTK, as is found in triple-negative breast cancer (e.g., in MDA-MB-468 cells, which do not express Her2), proliferative or metastatic signalling could be driven by the uncontrolled impact of monomeric Grb2-mediated Shp2 activation." (PMID 33795832, 2021).
urothelial carcinoma (1 paper, 2021). A malignant neoplasm derived from the transitional epithelium of the urinary tract (urinary bladder, ureter, urethra, or renal pelvis). "Recently it was shown in urothelial carcinoma cells that SH3BGRL3 can only indirectly interact with EGFR following stimulation of the cells with EGF for 10–30 min and that this interaction occurs through Grb2." (PMID 34380438, 2021).
cancer (153 papers, 2005 to 2026). A tumor composed of atypical neoplastic, often pleomorphic cells that invade other tissues. "These effectors, such as PI3K and Grb-2, play crucial roles in diverse cancer-associated processes, encompassing cell survival, proliferation, and migration." (PMID 38272982, 2024). "This combination of GRB2 depletion and PARPi treatment enabled longer survival and less cancer-associated complications." (PMID 38459011, 2024). "A handful of studies have shown that the promotion of SHP2/Grb2 interaction is associated with cancer development." (PMID 35589677, 2022). "GRB2 is a ubiquitously adaptor protein, which is implicated in numerous malignant tumors, such as multiple myeloma, lung cancer, hepatocellular carcinoma, esophageal squamous cell carcinoma, pancreatic cancer and so on." (PMID 35465829, 2022). "Intriguingly, DRD4 and GRB2 were two mostly shared genes mediating the associations between mirtazapine and cancers." (PMID 34131148, 2021). "MiR-27-3p and Grb2 have been reported to be associated with the Ras-ERK pathway across diverse cancers." (PMID 34162761, 2021). "GRB2 encodes growth factor receptor-bound protein 2 and has been described in cancers relatively frequently; as such, anti-cancer therapeutics targeting GRB2 are currently in development." (PMID 31974418, 2020). "An impaired interaction between Gab2 and Grb2 is implicated in the onset and progression of different types of cancers, thus being a valuable potential anticancer drug target." (PMID 33171874, 2020). "In this study, Met-derived docking-specific variants were used to define the cancer properties induced upon the RTK-mediated engagement of the Grb2 or Shc adaptor proteins in IECs." (PMID 24708867, 2014). "Mutation of the GRB2 docking site pY1356 uncouples GRB2 interaction and rescues the metastatic potential of cancer cells." (PMID 23826330, 2013). "Most cancer malignancies are caused by abnormal signaling of the Grb2 adaptor molecule." (PMID 36676027, 2022). "Moreover, a number of reports have indicated that GRB2 overexpression is associated with poor prognosis in cancers including ESCC." (PMID 34345012, 2021). "We also determined whether the ERK activities controlled by Grb2 SUMOylation were associated with tumorigenesis in CMT-93 cancer cells." (PMID 24775912, 2014). "Therefore, we investigated the evolutionary history of cancer associated gene sequences across 384 mammalian taxa, to detect signatures of selection across categories of oncogenes (GRB2, FGL2 and CDC42), tumour suppressors (LITAF, Casp8 and BRCA2) and immune genes (IL2, CD274 and B2M)." (PMID 38773187, 2024). "Studies performed predominantly in fibroblast and breast cancer cell models have revealed that Grb2 and Shc adaptor proteins are among the signaling proteins that, upon recruitment by activated RTKs, mediate events directly linked to the initiation and progression of cancer." (PMID 24708867, 2014). "Here, we investigated the interaction between coumarin and the monomeric form of Grb2 under two physiologically relevant pH conditions (7 and 8), corresponding to healthy and cancer cell environments, respectively." (PMID 41726597, 2026). "The adaptor protein Grb2 is a critical regulator in signaling pathways responsible for cell growth and proliferation, making it a key target in various carcinomas." (PMID 41835553, 2026). "SHCBP1 is reported to activate MAPK/ERK/MEK through Shc, Grb2, Sos, and Kras signaling pathways in cancer cells." (PMID 40157910, 2025). "Taken together, our integrative strategy revealed ITGA2B, FLNA, GRB2, FCGR2A, and APP as high-confidence, FDA-targetable candidates that intersect cancer-associated platelet education with pro-metastatic platelet signaling." (PMID 41226816, 2025). "A critical PPI, controlling cell growth and proliferation in breast and other cancers, occurs between growth factor receptor‐bound protein 2 (Grb2) and a polyproline II (PPII) helix embedded in Gab2." (PMID 40377959, 2025).
cancer (continued). "PIK3R2 plays a crucial role in regulating cell growth, survival, proliferation, motility, and morphological dynamics, while GRB2 is involved in cancer cell mobility, migration, and invasion through growth factor signal transduction." (PMID 40733070, 2025). "Tumours with decreased expression of growth factor receptor-bound protein 2 (GRB2) reflected the same response to PARPis as BRCAm cancers." (PMID 40192976, 2025). "Having established functional and mechanistic roles for GRB2 during RF stress that restrict inflammatory cytokine release, we directly investigated immune surveillance of PARPi-treated cancer cells with low GRB2 in a whole animal setting." (PMID 38459011, 2024). "It is worth noting that among these genes, STAT3 is the known cancer driver gene, while SHC1 and GRB2 are cancer driver genes predicted by SGCD (ranked in the top 50 predicted cancer driver genes of MULTINET)." (PMID 39751645, 2024). "Overexpression of GRB2-GFP exerted effects on both basal and stimulated EML4-ALK cancer cells, in a manner dependent on GRB2 expression levels." (PMID 39488530, 2024). "GRB2 alleviates oncogenic replication stress, and in doing so, averts cancer immune destruction by inhibiting cGAS/STING and pro-inflammatory cytokine production." (PMID 38459011, 2024). "Enriched pathways associated with cluster 2 include “Signaling by ERBB2 in Cancer” (Holm-adjusted p = 0.045), “PI3K events in ERBB2 signaling” (Holm-adjusted p = 0.013), and “GRB2 events in ERBB2 signaling” (Holm-adjusted p = 0.013)." (PMID 38271343, 2024). "The research has shown that cancer driver genes are often found together in the same modules instead of being randomly scattered, and this suggests that the identified cancer genes SHC1 and GRB2 are promising candidates for cancer driver genes." (PMID 39751645, 2024). "The C-SH3 is particularly important as it mediates the binding between Grb2 with Gab1 and Gab2, an interaction that appears to be upregulated in several forms of human cancers." (PMID 38432639, 2024). "As briefly recapitulated previously, the case of Grb2 is particularly instructive as this protein represents a critical target for several types of human cancers, and the folding and function of its C-terminal SH3 domain has been extensively characterized." (PMID 38432639, 2024). "Yet GRB2 nuclear activities and mechanisms as well as their possible connections to cancer are largely undefined." (PMID 38459011, 2024). "Although GRB2 is not in the list of druggable candidates, some studies have shown that GRB2 is a promising cancer therapeutic target." (PMID 37172717, 2023). "Out of the eight cancer-related genes, we identified that pleural fluid GRB2, WEE1, RNF4, and DUSP6 mRNA levels were significantly different between patients with MPE and benign PE by using two-independent sample t-tests." (PMID 37095178, 2023). "BP1001 is a liposome-incorporated antisense oligodeoxynucleotide designed to inhibit the expression of growth factor receptor-bound protein-2 (Grb-2), an essential oncoprotein in cancer cell signaling." (PMID 36918935, 2023). "GRB2 is a critical actor in normal cell function, as well as in pathological processes leading to various cancers and chronic diseases." (PMID 36864087, 2023). "Our data indicate a need to better understand the role that perturbation of the Grb2:Grb3-3 ratio, and in particular the specific role of Grb3-3, play in establishing Ras signalling in disease states such as cancer." (PMID 36171279, 2022). "The most relevant FGFR-downstream pathways in cancer are activated by the FGFR substrate 2 (FRS2) mediated binding of growth factor receptor bound protein 2 (GRB2)." (PMID 35955806, 2022). "Grb2 was previously shown to be activated by ALK for cancer cell transformation and to interact with UVRAG, a regulator of the early stages of autophagy and autophagosomal maturation." (PMID 33452442, 2021).
cancer (continued). "It has been reported that elevated expression of Grb2 was identified in various cancer cells, including breast cancer, GC and esophageal squamous cancer." (PMID 34162761, 2021). "We further undertook a study of GRB2 expression in stromal cells using an image containing both cancer and stromal cells." (PMID 33707553, 2021). "In fact, previous studies have also reported the key role played by Grb2 in regulating cancer metabolism and heart fibrosis." (PMID 33829014, 2021). "We chose to complete many key structures with higher resolution crystal structures, and then the docking site was selected in the SH3 region of GRB2, so as to influence the cell signal transduction events and achieve the therapeutic effect of cancer." (PMID 33649481, 2021). "We found that high expression of GRB2 protein was observed only in cancer cells, although it varied widely between samples." (PMID 33707553, 2021). "The interaction between the C-SH3 domain of Grb2 and Gab2 is of crucial importance for cell physiology and its implications for cancer onset and development are well known." (PMID 33171874, 2020). "Grb2 has repeatedly been investigated in the context of cancer; however, with contradictory results." (PMID 32466394, 2020). "As for GRB2, this gene participates in multiple cancer related pathway, such as chemokine signaling pathway, ErbB signaling pathway, MAPK signaling pathway and Jak-STAT signaling pathway." (PMID 31888623, 2019). "N-cadherin induces EMT and cancer stem cell–like characteristics by activating ErbB pathway through upregulating the level of growth factor receptor-bound protein 2 (GRB2), SHC-transforming protein and ERK." (PMID 31547193, 2019). "The underlying mechanism can be related to the downregulation of PIK3CA and GRB2, which are crucial for growth, proliferation, survival, and migration of cancer cells." (PMID 31719636, 2019). "Grb2 was shown to be highly and ubiquitously expressed in major tissues and various cancers, as shown by data obtained from the GeneCards and cBioPortal database, respectively." (PMID 29575431, 2018). "To determine the role of activated BST-2 in cancer cells, we started by investigating the level of GRB2 – a docking protein that binds to phospho-tyrosine residues of activated receptors and recruits ERK1/2 to the signaling complex." (PMID 28300825, 2017). "Overexpression of the Grb2 protein and amplification of the GRB2 gene have been reported in human cancer cell lines." (PMID 28346375, 2017). "The enrichment analysis shows that GRb2 participates in multiple cancer related pathway, such as chemokine signaling pathway, ErbB signaling pathway, MAPK signaling pathway, Jak-STAT signaling pathway." (PMID 28938536, 2017). "We identify BST-2/GRB2/ERK/BIM/Cas3 as the pathway regulating BST-2-mediated cancer cell adhesion, anoikis resistance, anchorage-independency, cell survival and growth." (PMID 28300825, 2017). "Human cancer tissue analysis shows a significant increase in Grb2 phosphorylation in high-grade pre-metastatic tumours, further highlighting the importance of mGrb2 in signal transduction and cancer progression." (PMID 26103942, 2015). "The self-association/dissociation of Grb2 represents a switch that regulates MAP kinase activity and hence controls cancer progression." (PMID 26103942, 2015). "The Tpr-Met and the Grb2- and Shc-specific docking oncoproteins are all predicted to promote cancer features in IECs by engaging similar signaling pathways." (PMID 24708867, 2014). "In this study, we provide evidence that Met-driven oncogenic activation of Grb2 or Shc signaling leads to the neoplastic transformation of normal IECs and induces multiple redundant hallmarks of cancer in these cells." (PMID 24708867, 2014). "Overall, these results identify Grb2 and Shc as central signaling effectors of Met-driven progression of intestinal epithelial-derived cancers." (PMID 24708867, 2014).
cancer (continued). "Functionally, GRB2 contributes to tumor growth, invasiveness and metastasis making it a high priority target for anti-cancer drug development." (PMID 24391994, 2013). "Molecules that bind to GRB2 protein and inhibit signal transduction have been demonstrated to reduce motility in vitro and to decrease cancer metastasis in animal models." (PMID 23922722, 2013). "Sall4, Grb2, β-catenin, and Stat3 are known to be expressed in tumor cells and their roles in cancer has been already studied." (PMID 20950440, 2010). "Dysregulation of this pathway is common in cancer, making Grb2 a compelling therapeutic target." (PMID 41726597, 2026). "Moreover, in the immune competent mouse model, PARPi treatment of cancer cells with low-GRB2 leads to an enhanced targeted destruction tumor cells by the host immune system compared to PARPi alone." (PMID 38459011, 2024). "Moreover in a syngeneic mouse metastatic ovarian cancer model, GRB2 depletion in the context of PARPi treatment reduced tumor burden and enabled high survival consistent with immune suppression of cancer growth." (PMID 38459011, 2024). "Analysis of human cancer tissues has revealed increased GRB2 phosphorylation in high-grade premetastatic tumors, suggesting that pY160 could serve as a potential predictive biomarker in personalized cancer therapy." (PMID 38540680, 2024). "Grb2-KD mice receiving Talazoparib showed a reduced cancer burden." (PMID 38459011, 2024). "The effects of these two Grb2 Affimers were explored in two cancer cell lines, U-2-OS and HeLa." (PMID 39550397, 2024). "Additionally, growth factor receptor binding protein 2 (GRB2), a long-described binding partner of Tks4, plays a significant role in cancer signaling pathways." (PMID 39234565, 2024). "The widespread involvement of GRB2 positions it as a novel target for anti-cancer treatments, as blocking any substrate in the GRB2-mediated signaling cascade could downregulate the entire carcinogenic pathway." (PMID 38540680, 2024). "Therefore, the SUMOylation of GRB2 is also expected to become a new target for disease treatment or cancer therapy in the future." (PMID 38540680, 2024). "To investigate if GRB2-mediated regulation of AGO2 could affect the cell cancer phenotype we performed migration assays in HEK293T cells which were overexpressing GFP-tagged AGO2 WT or the GRB2-binding-deficient mutant GFP-AGO2 4A." (PMID 37328606, 2023). "Additionally, RHOV activates EGFR signaling through GRB2, thereby regulating cancer cell migration and promoting metastasis in TNBC." (PMID 37596964, 2023). "Thus, a new role for GRB2 is established with implications for cancer pathogenesis through regulation of miRNA biogenesis and oncogene expression." (PMID 37328606, 2023). "Alterations of Grb2 protein can have a crucial role in cancer development." (PMID 36012138, 2022). "At the same time, GRB2 is conventionally known to play oncogenic roles in cancers." (PMID 35465829, 2022). "In these tumors, overexpression of Grb2 is very important for cancer development and its inhibition could represent a novel strategy of treatment." (PMID 36012138, 2022). "Indeed, the different mechanisms of this activation contribute to cancer cells proliferation and induce resistance by over-activating Grb2/RAS/RAF/MAPK cascades." (PMID 35267503, 2022). "Growth factor receptor-bound protein 2 (Grb2), a universally expressed adaptor protein, which plays a pivotal downstream mediator role in a variety of oncogenes signaling pathways and has a significant effect on signal transduction in normal and cancer cells." (PMID 33649481, 2021). "All these findings suggest that reducing the GRB2 level could arrest the malignant growth of cancers, which may provide a potential treatment strategy for ESCC." (PMID 34345012, 2021). "High expression of GRB2 was detected only in cancer cells, whereas only weak expression was observed in stromal cells, suggesting that GRB2 is expressed mainly by cancer cells." (PMID 33707553, 2021).